TNF (tumor necrosis factor)
Diseases named in the same sentence as TNF in open-access papers (continued):
Sharing a sentence is not in itself a finding about the gene and the disease.
cognitive decline (continued). "We therefore evaluated this TNF-α-related effect in the ACC and found a reduction in the expression of GluR1 in rats infused with H-αSynOs, further supporting the reduced neuronal activity in this area and suggesting a possible mechanism of inflammation-mediated cognitive decline." (PMID 36078036, 2022). "TNF-α-mediated inflammation is recognized as a significant mechanism of AD induction, and anti-TNF therapy has been shown to decrease the pathological brain changes in rodent models of AD, as well as to slow down cognitive decline and improve everyday function in patients with AD." (PMID 32485815, 2020). "Individuals with low serum levels of TNF-α showed no cognitive decline over the 6 months." (PMID 30930767, 2019). "Therefore, the increase in TNF-α levels induced by GFAP-Cre-mediated hepcidin depletion may account for the decrease in the proliferation of hippocampal NSCs, thus contributing to abnormal hippocampal development and cognitive decline in mice." (PMID 38195497, 2024). "Hence, the improvement in cognitive decline observed upon anti-TNF-α therapy may be a direct central effect and may not be subsequent to the better management of pain in RA patients." (PMID 33530359, 2021). "On the other hand, negative correlation of inflammation biomarkers, i.e., TNFα, with FA in the body and isthmus of the corpus callosum has been also found in healthy aging subjects by a TBSS analysis, showing that systemic inflammation is not necessarily associated with cognitive decline." (PMID 28670271, 2017). "Participants with the highest inflammatory mediators tertile were also more likely to have cognitive decline compared with participants with the lowest tertile for IL-6 and for CRP but not for TNF-α." (PMID 30930767, 2019).
lymphoma (277 papers, 2007 to 2026). A malignant (clonal) proliferation of B- lymphocytes or T- lymphocytes which involves the lymph nodes, bone marrow and/or extranodal sites. "We showed that pro-inflammatory TNF-α was elevated in lymphomas with thrombosis and inversely associated with the IPI." (PMID 40076681, 2025). "Genome-wide association studies (GWAS) further highlight shared susceptibility loci between ADs and lymphoma, particularly in regions regulating immune modulators such as TNF-α and IL-10." (PMID 41567225, 2025). "Of particular note, integrative analyses have consistently identified aberrant activation of the IL-17, TNF, and oestrogen signalling pathways in ADs-associated lymphoma patients, suggesting that these pathways play pivotal roles in disease pathogenesis." (PMID 41567225, 2025). "Patients with lower IPI scores already have largely increased TNF-α in lymphomas with increased risk for thrombosis." (PMID 40076681, 2025). "While RA and TNF-alpha inhibitors have historically been associated with an increased risk of lymphoma, chronic lymphocytic leukemia/small lymphocytic lymphoma (CLL/SLL) is infrequently seen." (PMID 40893576, 2025). "Those significant limitations highlight the complexities in interpreting RCT-based data on the risk of lymphoma in anti-TNF-α therapy." (PMID 39064585, 2024). "In response, this systematic review addresses that critical gap in the knowledge by examining the available evidence regarding the potential link between anti-TNF-α medications and the risk of all types of lymphoma among patients with RA." (PMID 39064585, 2024). "Taken together, those findings highlight the complex relationship between anti-TNF-α therapy and the risk of lymphoma and underscore the need for careful patient monitoring and risk assessment in treating RA." (PMID 39064585, 2024). "The use of three comparator groups—general population, patients with RA on anti-TNF-α therapy, and patients with RA on methotrexate and/or placebo—provided a more significant assessment of the risk of lymphoma among recipients of anti-TNF-α." (PMID 39064585, 2024). "A recent systematic review of a meta-analysis of 261,698 patients found that both anti-TNFα drugs and thiopurine were associated with an increased risk of lymphoma." (PMID 39204132, 2024). "This systematic review and meta-analysis assesses the risk of lymphoma in patients with RA treated with anti-TNF agents versus patients treated with methotrexate and/or a placebo." (PMID 39064585, 2024). "Some studies have proposed a potential association between anti-TNFα biologic treatment and an increased risk of lymphoma." (PMID 38610706, 2024). "This suggests that observational studies that have shown an association between lymphoma and anti-TNF have methodological flaws and that the results remain biased." (PMID 38673824, 2024). "This systematic review and meta-analysis provides important insights into the risk of lymphoma associated with anti-TNF-α therapy in patients with RA." (PMID 39064585, 2024). "Given the described risk’s clinical significance and the associated implications for treatment decision making, there is a pressing need to systematically synthesize existing evidence about the relationship between anti-TNF-α and the risk of lymphoma." (PMID 39064585, 2024). "A 2018 meta-analysis revealed the presence of a strong correlation between lymphoma risk and anti-TNF exposure." (PMID 37206474, 2023). "In lymphoma, pyrexia is a paraneoplastic effect thought to be associated with the release of cytokines such as IL-6 and TNF-α, and those cytokines were manifestations of tumor-related inflammation." (PMID 37909016, 2023). "Anti-TNF and thiopurine medication appears to cause a small but discernible increase in the chance of lymphoma in IBD patients, albeit this risk cannot be precisely measured." (PMID 37206474, 2023).
lymphoma (continued). "According to a French national cohort study of an estimated 1,89,289 patients affected by IBD, those receiving combination therapy of thiopurine and anti-TNF agents had a 6-fold greater risk of lymphoma compared to those receiving monotherapy of either drug." (PMID 37206474, 2023). "Inflammatory changes including production of a proliferation inducing ligand (APRIL), a member of the tumor-necrosis factor (TNF)-family, by macrophages, have been associated with lymphoma development." (PMID 37249755, 2023). "The risk of lymphoma has also been investigated; however, assessing the risk of anti-TNF monotherapy can be difficult because many patients have been previously treated with TPs." (PMID 36765829, 2023). "Anti-TNFα and thiopurines combination therapy seems to be associated with a higher lymphoma risk than thiopurines or anti-TNFα monotherapy." (PMID 37370740, 2023). "In 2020, a meta-analysis including 4 observational studies confirmed that anti-TNF therapy was associated with a higher rate of lymphoma than that in IBD patients unexposed to anti-TNFs with a pooled IRR of 1.52/1000 PY." (PMID 36983432, 2023). "Data on the risk of lymphoma in IBD patients exposed to anti-TNFα in combination with methotrexate are insufficient." (PMID 37370740, 2023). "The state of immune activation associated with IBD and some therapies used in IBD, such as thiopurines and anti-TNF drugs, have been described as possible factors that contribute to the increased risk of lymphomas in patients with IBD." (PMID 36765708, 2023). "The risk of lymphoma was significantly higher among patients exposed to combination therapy (HR 6.11) than in those exposed to thiopurine monotherapy (HR: 2.60) or anti-TNF monotherapy (HR: 2.41) compared to unexposed patients." (PMID 36983432, 2023). "Despite the findings emerging from this study, thiopurines and anti-TNF medications should be used when clinically necessary, either alone or in combination, notwithstanding the minimal absolute risk of lymphoma." (PMID 37206474, 2023). "A meta-analysis of four high-quality observational studies reported a similar risk of lymphoma with anti-TNF monotherapy and thiopurine monotherapy." (PMID 35160280, 2022). "These two studies research the risk of infections and lymphoma associated with thiopurines and anti-tumor necrosis factor (TNF) agents, used alone or in combination, providing important evidence for the management of IBD." (PMID 35761289, 2022). "In a meta-analysis, the risk of lymphoma was higher in patients treated with combination therapy than in those with TP o anti-TNF monotherapy (RR= 1.10; 95% CI: 1.03–2.81; p = 0.039)." (PMID 34336887, 2021). "Only four studies found a significant association of anti-TNF drug with lymphoma or groups of cancers including lymphoma." (PMID 30941038, 2019). "The identification of lymphoma associated with the TNF-α agents was recognized in post marketing surveillance." (PMID 31885858, 2019). "We also observed CD patients had higher hazard ratios of surgery than UC patients, which suggested that CD patients had more severe disease activity and were more likely to receive immunosuppressants and anti-TNF agents that increased their risk of lymphoma." (PMID 31831015, 2019). "Conversely, the association between the use of anti-TNF agents and the development of lymphoma remains undetermined." (PMID 30941038, 2019). "In this systematic review, we analyzed the evidence coming from observational studies supporting an association between the use of anti-TNF drugs and lymphoma in patients with IBDs." (PMID 30941038, 2019). "Polymorphisms in TNF have been reported to contribute partially to the development of lymphosarcoma and PVL in BLV infected cattle and early elimination of BLV in experimentally infected sheep." (PMID 29439661, 2018).
lymphoma (continued). "Although the safety and efficacy of anti-TNFα agents have already been established, the risk of lymphoma appears higher in patients treated with immune-modulating agents." (PMID 29954352, 2018). "On the other hand, in more advanced stages of the disease, the loss of multifunctionality and the loss of IFN-γ+ /TNF-α+ T–lymphocytes were observed in cases of lymphoma (p < 0.05)." (PMID 30337929, 2018). "Accumulating researches have pointed out that in lymphoma patients, TNF-α accumulation is associated with lymphoma progression and serum sIL-2R is a predictor of poor outcome in DLBCL patients." (PMID 29109622, 2017). "Possible additional increased risk for lymphoma associated with TNF inhibitors was also reported in few cases." (PMID 27630714, 2016). "In lymphoma, IL-10 -3575A and TNF -308G increase the risk of DLBCL, and CTLA-4 + 49 A > G increases the risk of MALT lymphoma." (PMID 26108796, 2015). "There is growing evidence that A20 mutations correlate with several types of lymphomas and elevated TNFα secretion is characteristic of many cancers." (PMID 24324544, 2013). "Inflammatory activity of the underlying disease is the main risk factor of lymphoma in RA, however, and anti-TNF therapy is used for patients with the most active disease." (PMID 19470150, 2009). "Current data are insufficient to establish a causal relationship between anti-TNF and the development of lymphoma." (PMID 27942275, 2009). "In those studies that specifically evaluated the effects of tumor necrosis factor (TNF) antagonists on lymphoma risk, there was a higher risk in RA patients receiving anti-TNF therapy compared with the general population, with SIRs of 2.9 and 11.5." (PMID 18433475, 2008). "In addition, TNF-α antagonists have been linked to a higher risk of opportunistic infections and lymphomas in patients with IBD, particularly when used in conjunction with immunosuppressive therapies." (PMID 40283885, 2025). "Anti-inflammatory agents targeting IL-1β or TNF-α, along with anticoagulants, may represent promising avenues for reducing thrombosis risk in lymphoma patients." (PMID 40076681, 2025). "Interleukin-1β was elevated across lymphomas and inversely correlated with the Khorana score for venous thromboembolism, while increased tumor necrosis factor-alpha (TNF-α) was inversely associated with the International Prognostic Index (IPI) in thrombosis-associated lymphomas." (PMID 40076681, 2025). "Exploring biological mechanisms and identifying biomarkers that predict the risk of lymphoma will further enhance current understandings of the lymphoma risk in RA patients treated with anti-TNF-α agents and inform personalized treatment approaches for patients with RA." (PMID 39064585, 2024). "Although IBD itself is not considered a risk factor for gastrointestinal lymphoma, long-term use of immunosuppressants and TNF inhibitors may increase the risk of lymphoma." (PMID 39329122, 2024). "Lymphomas induce an inflammatory state characterized by immune dysregulation and the release of pro-inflammatory cytokines, such as interleukin-6 (IL-6), IL-10, and tumor necrosis factor-alpha (TNF-α), which are associated with the development of NHL." (PMID 39110199, 2024). "Furthermore, when the researchers transferred Eubacterium rectum-deficient microbiota from lymphoma patients into mice, it triggered inflammation and TNF production." (PMID 38415259, 2024). "In a comprehensive analysis of seven observational studies on treatments for RA, with a total population of 177,963 patients with RA, the risk of lymphoma among patients receiving anti-TNF-α agents was compared with the risk of ones receiving conventional therapy." (PMID 39064585, 2024). "By synthesizing data from diverse studies and employing robust statistical analyses, the review seeks to clarify whether using anti-TNF-α agents confers an increased risk of lymphoma compared with conventional treatment modalities." (PMID 39064585, 2024).
lymphoma (continued). "However, subsequent studies have shown that the relationship between anti-TNF drugs and increased risk for lymphoma is still questionable and difficult to demonstrate, including the fact that most patients were exposed to other medications, mainly thiopurines." (PMID 38673824, 2024). "The review included both RCTs and observational studies in order to enhance the precision of information concerning the risk of lymphoma in patients with RA undergoing treatment with anti-TNF-α agents compared with patients treated with methotrexate and/or a placebo." (PMID 39064585, 2024). "Moreover, combo-therapy significantly increases the risk of lymphoma when compared to anti-TNF or TP monotherapy (aHR = 2.53, p < 0.001; and aHR = 2.35, p < 0.01, respectively)." (PMID 36765829, 2023). "However, the risk of lymphoma associated with combined anti-TNF and thiopurine therapy is significantly higher than that of thiopurine or anti-TNF monotherapy." (PMID 36983432, 2023). "For what concerns anti-TNF drugs, it is unclear whether the greater risk of lymphoma is due to biologic therapy itself, or whether the augmented risk is explained by past or concomitant exposure to immunosuppressants, namely thiopurines." (PMID 37206474, 2023). "Moreover, TNF-α operates as a growth factor for lymphoma and polymorphisms within TNF-α genes are associated with the higher risk of diffuse large B cell lymphoma (DLBCL), which is another frequent type of LPD in RA patients." (PMID 35062319, 2022). "However, combination use of anti-TNF therapy and thiopurines is associated with increased risk of malignancies including skin cancer and lymphoma." (PMID 35120446, 2022). "However, the role of anti-TNF-α therapies in increasing the risk of lymphoma has been described and seems clear in patients with autoimmune diseases, such as inflammatory bowel disease or rheumatoid arthritis." (PMID 36555171, 2022). "In particular, anti-TNF therapy increased the risk of lymphoma development in IBD patients." (PMID 33917839, 2021). "There is great interest in whether treatment with TNF inhibitors further increases the risk of lymphoma in patients with RA." (PMID 33535498, 2021). "The hypothesis of a role of endotoxin exposure in the etiology of some lymphoma arises from the observation that TNF-α polymorphisms, resulting in TNF-α over-expression, are associated with an increase in DLBCL risk." (PMID 33103203, 2021). "Additionally, the level of TNF-a is associated with poor prognosis and can expect treatment outcome in lymphoma patients." (PMID 32986381, 2020). "This ability to compensate for the loss of extrinsic cytokine-derived signals is supported by recent data showing that co-culture of DLBCL cells with human lymph node-derived FRC increased their expression of podoplanin, a process linked to lymphoma secreted lymphotoxins and TNF-α." (PMID 33628205, 2020). "Moreover, Mariette and colleagues suggested that the anti-TNFα Abs increase the risk of lymphoma 2- to 3-fold compared with the general population." (PMID 31194726, 2019). "The risk of lymphoma is still a major concern in patients using anti-TNFα agents." (PMID 29954352, 2018). "In 2009, a great scientific debate regarding the safety of TNF blockers started, prompting the FDA to issue a warning regarding a possible association between the use of TNF blockers and the development of lymphoma and other cancers in children and young adults with JIA." (PMID 30587248, 2018). "Ophthalmologists should be aware of the relationship between immunosuppression via anti-TNFα medication, and an increased risk for lymphoma, especially in patients with underlying rheumatologic disorders, and especially in cases with suspected chronic refractory uveitis." (PMID 29954352, 2018).